IL6 (interleukin 6)
Diseases named in the same sentence as IL6 in open-access papers (continued):
Sharing a sentence is not in itself a finding about the gene and the disease.
tumor (continued). "IL-6 promotes tumor progression through activating a variety of downstream signaling events including JAK-STAT, PI3K-Akt and Ras-Raf-MEK-MAPK cascades." (PMID 37047623, 2023). "A hypoxic TME releases pro-angiogenic factors, including VEGF, FGF, and PDGF, resulting in tumor vascularization via the activation of IL-6 and the inhibition of IL-12." (PMID 37107298, 2023). "It has been reported that CD90+ fibroblasts are the main source of IL-6, which is a multi-effector cytokine involved in the tumor growth process." (PMID 36747131, 2023). "APCs contribute to IL-1, IL-6, IL-8, and IL-10 signaling along with macrophages and DCs in innate immunity and tumor cells in senescence." (PMID 37894479, 2023). "Mouse models showed that by stimulating cells in TME, IL-6 can foster immunosuppressive conditions, mostly by mediating cross-talk between tumor cells and activated tumor-infiltrating cells such as CAFs." (PMID 37958406, 2023). "The presence of the gut microbiota has been shown to inhibit IL-6 and IL-1, thereby suppressing the differentiation of Th17 cells and promoting tumor progression." (PMID 37680632, 2023). "STAT3, a member of signal transducer and growth factors (STAT), is one of the main transcription factors that transmit the signals of several cytokines, particularly IL-6 in KRAS-mutant tumor cells." (PMID 36899885, 2023). "Other reviews have also indicated that inflammatory cytokines, such as interleukin(IL)-1, IL-6, IL-10, tumor necrosis factor-α, macrophage migration inhibitory factor, and transforming growth factor-β, are involved in tumor initiation and progression." (PMID 36855430, 2023). "To determine the redundancy of serum cytokine abundance for tumour monitoring, we checked the correlations of IL-6, IL-8 and IL-10 with these two ctDNA parameters." (PMID 37120670, 2023). "In tumor lysates, IL-6 decreased significantly in the groups treated with 12.5 mg/kg (p < 0.001) and 25 mg/kg (p < 0.05)." (PMID 38137888, 2023). "Several studies have indicated that interleukin-6 (IL-6) and interleukin-8 (IL-8) secretion promote multiple drug resistance while blocking these cytokines inhibits tumor cell viability and migration." (PMID 37958571, 2023). "Another SERM, bazedoxifene, was shown to have the function of inhibiting STAT3 phosphorylation and STAT3 DNA binding, inducing apoptosis, and suppressing tumor growth in PAAD cells with persistent IL6/GP130/STAT3 signaling." (PMID 36817451, 2023). "Nevertheless, vCAFs were found to actively interact with tumor cells via the pro-invasive IL6/IL6R axis." (PMID 36980203, 2023). "The secretion of pro-inflammatory factors such as TNF-α, IL-1β and IL-6 regulated the tumour microenvironment and exerted anti-tumour effects." (PMID 37386139, 2023). "STAT3, as a member of the STATs family, has a highly complex regulatory bioactivity and can exert pro-tumor, pro-inflammatory or anti-inflammatory and tissue repair effects through the activation of ligands such as IL-6/IL-10." (PMID 37081874, 2023). "A-FABP released from adipose tissue directly targets BCCs and enhances tumor aggressiveness in vivo by activating the IL-6/STAT3/ALDH1 pathway." (PMID 36880535, 2023). "The IL-6 antibody helps to reduce the levels of IL-6 in the body, which in turn helps to reduce the growth and spread of tumor cells." (PMID 37160480, 2023). "Pro-inflammatory cytokines, such as IL-6 and IL-16, exert significant influence on the tumor microenvironment and immune system." (PMID 37910571, 2023). "Immune cells are the primary source of IL-6; however, IL-6 can also be secreted by endothelial cells, fibroblasts, and certain tumor cells." (PMID 37822710, 2023). "On the one hand, IL‐6 is predominantly expressed by M1 cells in the early phase of inflammation and tumour development, having pro‐inflammatory and anti‐tumour effects." (PMID 36419386, 2023). "Another study found that IL-17-induced IL-6 production from the TEM triggers tumor-intrinsic STAT3, promoting tumorigenesis." (PMID 37686343, 2023).
tumor (continued). "In summary, this study explores the oncosuppressive function of TRIM29 in ESCC and reveals that TRIM29 downregulation due to hypermethylation of its promoter, positively regulates tumor suppresser gene ZNF750 via modulating IL6/STAT3 signaling pathway." (PMID 37365152, 2023). "These cells discharge pro-inflammatory substances such as tumor necrosis factor-α (TNF-α), interferon-γ (IFN-γ), IL-1β, and IL-6, which exacerbate local and systemic inflammation and act as potent tumor promoters." (PMID 37108477, 2023). "Serum IL-6 levels were found to correlate positively with tumour size and a poor prognosis in HCC patients." (PMID 36901717, 2023). "In the management to predict tumor resectability, the evaluation of tumor marker levels (IL-6, CA-125, and HE4) is paramount importance, particularly to achieve sub-optimal debulking surgery." (PMID 37792745, 2023). "Immune cells from MIP-treated mice produced higher amounts of IL-12 and IL-6 upon incubation with tumor lysate as compared to control mice." (PMID 37122749, 2023). "IL-6 promotes the polarization of macrophages towards the tumor-promoting M2 phenotype, which, in turn, produces the chemokine CCL-20." (PMID 38288125, 2023). "Intestinal cancer cells can also respond to the microbiota by inducing calcineurin-dependent IL-6 secretion, which promotes tumor expression of the co-inhibitory molecules B7H3/B7H4 that diminish anti-tumor CD8+ T cells." (PMID 36830830, 2023). "We found that the fibroblasts underwent activation induced by the TGF-β and the PDGF produced by the tumor cells, which increased their proliferation and IL-6 secretion." (PMID 37173963, 2023). "Blockade of the IL-6 signalling can enhance anti-tumour immunity and help in better control of disease, apart from prevention of irAE." (PMID 38414933, 2023). "In particular, NF-κB is overexpressed in multiple human cancers and activated STAT3 in tumor also induce IL-6." (PMID 37853413, 2023). "Typically, cardiac myxoma symptoms arise from flow obstruction, embolization, and the production of interleukin-6 by tumor cells; in addition, symptoms vary based on tumor size, location, and texture." (PMID 37730679, 2023). "In turn, IL6 enhances lactate metabolism of hypoxic tumor cells through the STAT3 pathway and upregulation of downstream MCT1 and LDHB, leading to resistance to SN38." (PMID 36831450, 2023). "Like IL-6, it is involved in tumor initiation, cell proliferation, promotion of angiogenesis, and metastasis." (PMID 38075864, 2023). "When adjusting for PS, tumor location, and stage, only IL-6 (HR = 1.25, 95% confidence interval (CI) 1.08–1.46) and IL-15 (HR = 2.23, 95% CI 1.48–3.35) remained significantly associated with OS." (PMID 36831406, 2023). "Cachectic mice have been described to be hypercoagulable partially due to tumor-derived IL-6, which is inducing thrombin expression." (PMID 37222464, 2023). "Tumor inflammatory cytokines from the primary site like IL-6 and IL-8 attract CTCs and leaky tumor neovasculature allows it to leak back into their primary site, where it secrets MMP-collagenase-1 and CXCL1 which stimulates tumor growth and angiogenesis." (PMID 37031192, 2023). "The nuclear factor kappa‐B (NF‐κB) pathway plays a substantial role in the production of inflammatory cytokines such as IL‐6 and IL‐8, thereby regulating the tumor microenvironment." (PMID 36627748, 2023). "We found that BC patients with T1 status primary tumour size were characterised by lower methylation status of the IL-6 promoter than BC patients with Ta and ≥T2 statuses (p < 0.05)." (PMID 37047238, 2023). "Laboratory examinations revealed elevated immunoglobulin G and C-reactive protein, and normal serum levels of tumor markers and interleukin-6." (PMID 38082371, 2023). "Maintenance of muscle mass is associated with decreased toxicity from chemotherapy and/or radiotherapy and increased anti-inflammatory myokines (e.g., IL-6), and suppresses tumour growth." (PMID 36839371, 2023).
tumor (continued). "M2b macrophage-secreted IL10 promotes Treg cell differentiation from naive T cells, whereas secreted IL6 activates Th2 cells, which promote tumor progression." (PMID 38035101, 2023). "In turn, iMSC secrete IL-6, LIF, and CCL2 that support tumor cell proliferation and IL-6, C3, ANXA-1, and VEGFa that modulate immune cell compartment, particularly myeloid cells." (PMID 38213954, 2023). "Meanwhile, of all the cytokines evaluated in the F3II tumor lysates, IL-6 was the only one that showed a significant decrease in tumor lysates in the groups treated with 12.5 mg/kg (p < 0.001) and 25 mg/kg (p < 0.05) of H. junceus scorpion venom." (PMID 38137888, 2023). "IL-6 has been found to be elevated in both the tumor microenvironment and systemically in many cancer models and in patients with a number of different forms of cancer." (PMID 38022653, 2023). "Although IL-6 plays a beneficial role in the body’s protective response against tumor cells, clinical studies have demonstrated a substantial decline in the efficacy of therapeutic drugs due to their interaction with IL-6." (PMID 37892997, 2023). "When specifically considering cancer, elevated IL-6 effects lead to proliferation, invasion, and metastasis of tumour cells, as well as suppression of antitumor immunity." (PMID 37794245, 2023). "In the local tumor microenvironment, production of tryptophan metabolites, secretion of cytokines including IL-6 and IL-10, and an increase in membrane expression of checkpoint proteins like PD-L1 result in local immunosuppression." (PMID 38188300, 2023). "Stimulating toll-like receptor 4 through lipopolysaccharide can augment the expression of cytokines, such as TNF-α, IL-6, and IL-10, and exacerbate TAMs to polarize toward M2, thus affecting tumor cell invasion and angiogenesis." (PMID 37345200, 2023). "Pro-inflammatory cytokine IL-6 is reported to stimulate the generation of tumor cells and stimulate angiogenesis." (PMID 37893013, 2023). "Tumor cells can initiate NFκB signaling, increasing IL-8 and reducing IL-6 secretion, mtDNA can activate cyclic GMP-AMP synthase and inflammasome pathways." (PMID 37292196, 2023). "For instance, IL-6, by activating the STAT3 signaling pathway, fosters M2 macrophage differentiation, which in turn is associated with activities that promote tumor growth and progression." (PMID 38035068, 2023). "TLR4- expression, in turn, was correlated with conferring resistance to the drug by promoting anti-apoptotic proteins, while IL-6 was found to endorse tumor progression inducing angiogenesis and proliferation via the STAT-3 pathway." (PMID 37900569, 2023). "IL-6 is produced by tumor cells and cells in the TME, such as fibroblasts, T and B cells, as well as myeloid, endothelial, and mesangial cells." (PMID 37190141, 2023). "It causes tumor inflammation through macrophages and increases the expression of TNF-a and IL-6, and also increases angiogenesis with high expression of CD31, VEGFR2, and HIF1a." (PMID 37361568, 2023). "IL-6 acts directly at IL-6R located on tumor cells to induce the expression of STAT3 target genes, and then drive tumor proliferation, survival and drug resistance." (PMID 37404767, 2023). "In this regard, it has been recently reported that “iron-retaining” M1 TAMs, showing a pro-inflammatory M1-like phenotype, induce tumor cell death and through the generation of ROS and pro-inflammatory cytokines (TNFα and IL-6)." (PMID 37377735, 2023). "It has been demonstrated that the IL6 blockade potentiates the anti-tumor effects of γ-secretase inhibitors in Notch3-expressing can be abrogated by the IL6R blocking antibody tocilizumab in breast cancer." (PMID 37898675, 2023). "Overall, the response to checkpoint inhibitor immunotherapy seems to be related to IL-6 baseline and on-treatment levels in several tumor types, possibly with the activation of common mechanisms." (PMID 36823670, 2023).
tumor (continued). "The growth of tumor cells stimulates the host to secrete interleukin-6 and other inflammatory factors, thereby increasing the synthesis of CRP in the liver." (PMID 37137949, 2023). "Here, we show that TAGLN overexpression can promote tumor spreading and tumor cell migration/invasion through the release of pro-inflammatory cytokines, namely interleukin-6 (IL-6), via NF-κB signaling pathway activation." (PMID 36990991, 2023). "IL-17A promotes the expression of IL-6, G-CSF, MFG-E8, and CXCL1 in NSCLC tumor tissues to increase tumor-associated neutrophils (TANs) infiltration and reduce the number of tumor-infiltrating lymphocytes (TILs), leading to drug resistance to PD-1 inhibitors." (PMID 37978543, 2023). "Air pollution–related pro-inflammatory mediators, such as tumor necrosis factor-alpha (TNF-α), interleukin-6 (IL-6), and interleukin-1β (IL-1β), create pro-inflammatory environments that promote tumor development." (PMID 38052753, 2023). "In our study, we have observed pronounced inflammation in mice with compound loss of LKB1 and PTEN, marked by increased levels of TGFβ and the inflammation marker IL-6 within the tumor microenvironment." (PMID 38136437, 2023). "Tumor-associated macrophages regulate inflammation and adaptive immunity by producing TGF-β1 and cytokines (TNF-α and IL-6) and promote angiogenesis and cell proliferation." (PMID 36874003, 2023). "Tumor IL6 mRNA (evaluated in n = 59 evaluable cases of RCC using in situ hybridization [ISH]) was observed mainly in epithelial and stromal cells." (PMID 36599350, 2023). "PGE2directly induces IL-10 release from macrophages, decreases IL-6 and TNF-α release, controls tumor-associated inflammation, and decreases the body’s anti-tumor immune response." (PMID 37153586, 2023). "By binding to the soluble receptor sIL-6R, IL-6 activates the JAK-STAT3 signalling pathway to promote tumour proliferation." (PMID 37752418, 2023). "The tumor promoting effect was then neutralized with an anti-IL-6 antibody, indicating that IL-6 is an important factor contributing to tumor expansion." (PMID 37744339, 2023). "Of note, IL-6 promotes the survival and proliferation of tumor cells and attenuates the antitumor ability of tumor-infiltrating immune cells through the IL-6/JAK/STAT3 signaling pathway in the TME." (PMID 38455086, 2023). "To better uncover the mechanism of IL-6/STAT3 signaling in TAM-educated tumor cells, we performed RNA-seq on MCF-7 cells after coculturing with TAMEV−Exo or TAMOE−Exo." (PMID 36797769, 2023). "All tumor cells secreted high levels of IL6, IL8, MCP1 and TGFβ, and lines with positive impact on DCs had lower levels of IL6 and MCP1 compared to lines with negative impact on DCs." (PMID 36891308, 2023). "B.adolescentis also boosted the cytotoxicity of macrophages against tumor cells and increased the expression of Il6 and Tnf in macrophages in a Dcn-independent way." (PMID 37464382, 2023). "IL-6 was detected in the tumor microenvironment and peripheral circulation of patients with KSHV-related malignancies." (PMID 37112991, 2023). "Inflammation is an effective inducer of EMT in tumors, TGF- β, TNF-α, IL‐1β, IL-6, IL-8, and other proinflammatory cytokines play a role in the initiation and maintenance of tumor EMT, increasing the invasiveness of cancer cells and promoting tumor metastasis." (PMID 37213276, 2023). "One report utilized primary monocytes in co-culture with CAR T-cells and their target tumor antigen to find an increase in myeloid-derived IL-6 secretion." (PMID 37914765, 2023). "ENO1 orchestrated the IL-6 secretion of macrophages via tumor cell-derived lactic acid and the paracrine ENO1/Toll-like receptor (TLR4) signaling pathway." (PMID 36614179, 2023). "Lactate secreted by CC cells mediates crosstalk between tumor cells and macrophages, which promotes the secretion of IL-1, IL-10, and IL-6, and upregulates the expression of hypoxia-induced factor-1, further promoting a suppressive phenotype." (PMID 37234990, 2023).
tumor (continued). "Results showed that these nanoparticles had increased IL‐12 and TNF‐α (antitumor chemicals) levels with a simultaneous decrease in IL‐6 and IL‐10 (pre‐tumor cytokines)." (PMID 38455223, 2023). "Prostaglandin-induced increased tumor formation was similarly reversed by indomethacin.Surgical stress increased plasma corticosterone and IL-6 levels and this effect was reversed by the cyclooxygenase inhibitor indomethacin." (PMID 37426669, 2023). "The tumor microenvironment can be affected by various interleukins such as factor IL-6, which has a role in tumorigenesis and development, and factor IL-1, which is involved in the angiogenetic and lymph-angiogenetic process, acting together with VEGF and FGF." (PMID 37445908, 2023). "Nevertheless, it has been reported that HPV-dependent IL-6 secretion by tumor cells increases radio sensitivity in some cancers, thereby improving treatment efficacy." (PMID 36769377, 2023). "Serum levels of tumor markers, coagulation function, renal function, thyroid function, and IL-6 were all normal, and antibodies to the human immunodeficiency virus (anti-HIV) were negative." (PMID 38082371, 2023). "These cytokines include TNF-α, IL-1β, IL-6, IL-8, IL-12, and IL-23, all of which inhibit tumor growth." (PMID 37759870, 2023). "As previously reported, MSCs, when mixed with tumor cells in a tumor-related microenvironment, differentiate into cancer-associated fibroblasts (CAFs) that produce VEGF, IL-6, TGFβ1, etc., resulting in pro-tumor activity." (PMID 37681882, 2023). "More importantly, tumor-derived IL-6 impairs the ketogenic response to reduced caloric intake, thus promoting a systemic metabolic stress response that blocks anti-cancer immunotherapy." (PMID 36766760, 2023). "Monocyte education by tumor cells through VEGF‐A also enhances secretion of IL‐6 and IL‐8, promoting tumor cell proliferation." (PMID 37088729, 2023). "Elevated expression of IL-6 leads to activation of JAK-STAT signaling, a cornerstone to cancer progression in particular linked to STAT3 activation, both through tumor growth and metastasis as well as modulation of immune surveillance." (PMID 37745296, 2023). "We further find that epigenetic priming induces increased tumor secretion of several key cytokines known to augment T and NK cell activation and cytotoxicity, including IL-6, IP-10 (CXCL10), KC (CXCL1), and RANTES (CCL5)." (PMID 37627156, 2023). "The accumulated body of evidence underscores the pivotal role of the IL-6/STAT3 signaling pathway in steering tumor metastasis and invasion." (PMID 37813837, 2023). "Compared with the neutrophils from RM1-derived tumors, the neutrophils in hybrid cell group showed an increased level of Il6/Jak/Stat3 signaling pathway which is usually hyperactivated in tumor infiltrating immune cells to inhibit antitumor immunity." (PMID 37138326, 2023). "IL-6 is a multifaceted cytokine produced by various cells during inflammation and immunological attack, and it is also relevant to the tumor microenvironment and anti-tumor immunity." (PMID 38089883, 2023). "IL-6 is released by tumor and stromal cells in an autocrine or paracrine manner and infiltrates the local area of solid tumors." (PMID 37817809, 2023). "We also found that in the docetaxel-treated mice tumor IL-6 signaling pathway was strongly signaling between fibroblasts/CAFs and endothelial cells with cancer cells." (PMID 37699010, 2023). "High expression of YAP in human HCC cells induces hepatocytes to secrete IL‐6 recruiting macrophages to the tumor, so suppression of YAP pathway blocks macrophage chemotaxis and infiltration in HepG2 xenograft tumors." (PMID 38098217, 2023). "Our previous study proved that intravenous injection of attenuated Plasmodium can inhibit LLC growth and prolong the survival of tumor-bearing mice by promoting the secretion of IL-6 and IL-12 and inhibiting tumor angiogenesis." (PMID 38274735, 2023).